RAB39B (RAB39B, member RAS oncogene family)
Description:
The small GTPases Rab are key regulators of intracellular membrane trafficking, from the formation of transport vesicles to their fusion with membranes. Rabs cycle between an inactive GDP-bound form and an active GTP-bound form that is able to recruit to membranes different sets of downstream effectors directly responsible for vesicle formation, movement, tethering and fusion. RAB39B is involved in autophagy and may function in autophagosome formation. Binds downstream effector PICK1 to ensure selectively GRIA2 exit from the endoplasmic reticulum to the Golgi and to regulate AMPAR composition at the post-synapses and thus synaptic transmission (By similarity). May regulate the homeostasis of SNCA/alpha-synuclein (By similarity).
Synonyms: BGMR; MRX72; WSMN; WSN; XLID72
Tractability: Small molecule: a structure with a bound ligand is known. Antibody: UniProt places it where antibodies can reach, with high confidence; its Gene Ontology location is reachable by antibodies, with medium confidence. PROTAC: ubiquitination databases record sites on it; its protein half-life has been measured.
Gene: Protein-coding gene on chromosome X (155,258,235 to 155,264,491, reverse strand). Ensembl gene ENSG00000155961.
Subcellular location: Cell membrane; Cytoplasmic vesicle membrane; Golgi apparatus; Cytoplasmic vesicle, autophagosome membrane; Autolysosome membrane
Pathways (Reactome):
Metabolism of proteins: RAB geranylgeranylation
Vesicle-mediated transport: RAB GEFs exchange GTP for GDP on RABs
Gene Ontology:
Molecular function: myosin V binding; protein binding; GTPase activity; G protein activity; GTP binding
Biological process: regulation of autophagy; synapse organization; vesicle-mediated transport; Rab protein signal transduction
Cellular component: autolysosome membrane; cytoplasmic vesicle membrane; Golgi apparatus; neuron projection; vesicle; autophagosome membrane; plasma membrane
Gene-disease validity (ClinGen):
ClinGen rates the evidence that RAB39B causes each of these diseases.
early-onset parkinsonism-intellectual disability syndrome (X-linked): Definitive. A basal ganglia disorder characterized by Parkinsonian-type symptoms (postural changes, tremor, rigidity), megalencephaly and variable intellectual deficit.
Homologues: Orthologues: chimpanzee RAB39B (100% identical), guinea pig RAB39B (100% identical), macaque RAB39B (100% identical), rabbit RAB39B (100% identical), dog RAB39B (99% identical), mouse Rab39b (99% identical), pig RAB39B (99% identical), tropical clawed frog rab39b (94% identical), zebrafish rab39ba (91% identical), zebrafish rab39bb (89% identical). Paralogues in human: RAB39A (78% identical), RAB42 (43% identical), RAB2B (42% identical), RAB11A (41% identical), RAB11B (40% identical), RAB14 (39% identical), RAB4B (39% identical), RAB8B (39% identical), RAB2A (38% identical), RAB8A (38% identical), RAB30 (38% identical), RAB33B (38% identical), and 56 more.
Diseases named in the same sentence as RAB39B in open-access papers:
RAB39B is named in the same sentence as 62 diseases in open-access papers, as found by Europe PMC text mining. Sharing a sentence is not in itself a finding about the gene and the disease. The quoted sentences say what the papers report.
Parkinson disease (28 papers, 2015 to 2025). A progressive degenerative disorder of the central nervous system characterized by loss of dopamine producing neurons in the substantia nigra and the presence of Lewy bodies in the substantia nigra and locus coeruleus. "We show that a central component of this system is Rab39, whose human homolog RAB39B is mutated in Parkinson's disease." (PMID 40841711, 2025). "Decreased function of RAB39B has been found to cause X-linked intellectual disability and early-onset Parkinson's disease through alpha-synuclein pathology." (PMID 37747131, 2023). "It is to be noted that RAB39B-related parkinsonism is caused by large-scale deletions, splicing abnormalities, and frameshift, nonsense, and missense mutations resulting in LOF." (PMID 37047309, 2023). "Between five and 10 patients had juvenile neuronal ceroid lipofuscinosis (JNCL), PTRHD1, RAB39B, X‐linked parkinsonism with spasticity, Alexander disease, dopa‐responsive dystonia‐parkinsonism (NR4A2), Fragile‐X syndrome or spastic paraplegia type 15 (SPG15)." (PMID 36699000, 2022). "For this reason, even when mutations of RAB39B are identified in adult patients referred to clinicians for parkinsonism, it is important to study the presence of symptoms of ASD." (PMID 34761259, 2022). "The deletion of a missense mutation, ∼45‐kb in RAB39B, RAB39B, and p.Trp186 stop mutation, reduces the function of RAB39B and improves the transfer to Parkinsonism." (PMID 34291612, 2021). "Linked to Rab39b mutation, Rab29, Rab5a, and Rab7 have been identified in inherited early-onset Parkinson’s disease with Lewy’s body." (PMID 34299299, 2021). "Rab7, Rab28, and Rab11 mutations are the primary cause of Charcot-Marie-Tooth disease and Rab39B in Parkinson’s disease." (PMID 34299299, 2021). "Loss of function mutations within the vesicular trafficking protein Ras analogy in brain 39B (RAB39B) are associated with rare X‐linked Parkinson’s disease (PD)." (PMID 32762091, 2021). "The distribution of Rab39b is consistent with human disease associations with parkinsonism and cognitive impairment." (PMID 32228644, 2020). "Mutations in RAB39B at Xq28 causes a rare form of X-linked intellectual disability (ID) and Parkinson’s disease." (PMID 32873259, 2020). "In mouse brain, Rab39b is expressed in cortical and hippocampal neurons, as well as in dopaminergic neurons of the substantia nigra, concordant with its association with parkinsonism and cognitive impairment in humans." (PMID 32873259, 2020). "Pathogenic variants in the gene encoding the small GTPase Ras analogue in Brain 39b (RAB39B) are associated with early-onset parkinsonism." (PMID 32228644, 2020). "Recently, RAB39B mutations were reported to be a causative factor in patients with Parkinson’s disease (PD)." (PMID 27694831, 2016). "Patients with a truncating mutation (p.Trp186stop mutation) of Rab39B display typical parkinsonism and early disease onset." (PMID 27509057, 2016). "Recently, two families were reported with early onset parkinsonism in males and a missense mutation (p.T168K) or a complete deletion of RAB39B." (PMID 26399558, 2015). "Lossof function mutations in RAB39B have been recently linkedto early onset of Parkinson’s disease." (PMID 41000401, 2025). "Finally, RAB39B gene mutations have been associated with a form of X-linked levodopa-responsive parkinsonism in combination with various degrees of intellectual disability." (PMID 37047309, 2023). "Subsequently, other RAB39B mutations were reported to be associated with the onset of parkinsonism." (PMID 36009486, 2022). "This evidence lends support to the hypothesis that RAB39B could play a more general role in neuromotor development, not limited to parkinsonism, stressing the importance of studying the pathogenic mechanisms that could be involved." (PMID 34761259, 2022). "To date, RAB39B is a proven but rare cause of Parkinsonism and intellectual disability in males." (PMID 34630269, 2021).
Parkinson disease (continued). "Interestingly, loss-of-function RAB39B mutations are causative of both X-linked mental retardation, showing comorbidity with autism spectrum disorder and epilepsy, and early onset Parkinson’s disease with synucleinopathy." (PMID 31651360, 2019). "Furthermore, Rab39B, one of the two isoforms of the Rab39 protein regulating basolateral exosome trafficking, is a causative gene product of Parkinson’s disease, further fortifying the links found between Parkinson’s disease and exosomes, and suggesting another link to those from polarized cells." (PMID 39286483, 2024). "The RAB39B gene has been reported to be mutated in ID patients with additional clinical features ranging from ASD, macrocephaly, seizures and/or early-onset parkinsonism." (PMID 34761259, 2022). "A role of RAB39B in parkinsonism has been subsequently described in several cases, usually, but not exclusively, in patients with RAB39B deletions/loss-of-function mutations." (PMID 34761259, 2022). "Mutations in the RAB39B gene cause X-linked intellectual disability (XLID), comorbid with autism spectrum disorders or early Parkinson’s disease." (PMID 34035473, 2021). "Whilst the role of RAB39B in cognitive function is relatively well established, a specific role in the pathogenesis of parkinsonism is yet to be elucidated." (PMID 32228644, 2020). "Mutations in RAB39B are known to be associated with X-linked intellectual disability (XLID), Parkinson’s disease, and autism." (PMID 33364235, 2020). "The collective results, to date, have implicated RAB39B in the development of EOPD and parkinsonism." (PMID 32670181, 2020). "Loss-of-function mutations in RAB39B were originally identified in two independent families who displayed the clinical features of early-onset Parkinson's disease (EOPD) with non-progressive intellectual disability and macrocephaly." (PMID 32670181, 2020). "Genetic investigations in larger parkinsonism/PD cohorts and longitudinal studies of individuals with cognitive impairment due to an altered dosage of RAB39B will be required to fully delineate the contribution of RAB39B to parkinsonism." (PMID 32670181, 2020). "Pathogenic whole gene deletion, missense, and splicing mutations in RAB39B (RAS-associated protein RAB39B, MIM* 300774) were identified in a few families with non-progressive intellectual disability, macrocephaly, and early-onset Parkinsonism in males (Waisman syndrome, MIM# 311510)." (PMID 34630269, 2021). "Therefore, additional investigations into the distribution of RAB39B in other human brain regions affected in parkinsonism beyond the SN and CPu could help define its role in disease mechanisms." (PMID 32228644, 2020). "One such gene, RAB39B, has been described in the literature in association with X-linked ID along with variable phenotypic manifestations including ASD, seizures, macrocephaly, delayed psychomotor development, and early-onset Parkinson’s disease or Parkinsonism." (PMID 29152164, 2017). "The mutants included in this study are ‘classical’ Parkinson disease genes, like LRRK2 and PINK1, and Parkinsonism genes that affect vesicle trafficking processes, including SYNJ1, DNAJC6/Aux. and RAB39B." (PMID 40178224, 2025). "Other mutations of RAB39B were detected in patients with intellectual disability of variable degree, autism, seizure, and macrocephaly without PD, as well as in male and female patients with early- or later-onset Parkinsonism, respectively, without intellectual disability." (PMID 34630269, 2021).
Intellectual disability (17 papers, 2012 to 2026). "Among monogenic forms, the gene RAB39B on Xq28 has been described as a rare cause of early‐onset PD associated to intellectual disability known as “Waisman's syndrome” (OMIM 311510)." (PMID 41074240, 2026). "Among them, RAB39B polymorphisms are known as rare causes of early‐onset PD associated with intellectual disability (Waisman's syndrome)." (PMID 41074240, 2026). "The genetic analysis identified loss of function mutation in Rab39B gene in two families with early-onset parkinsonism and intellectual disability and loss of Rab39B expression was observed in the postmortem brain from PD patients." (PMID 27509057, 2016). "Recently, Wilson and colleagues reported a missense mutation c.503C > A (p.Thr168Lys) and a complete deletion of RAB39B which was associated with a complex disease including atypical PD symptoms and intellectual disability." (PMID 27694831, 2016). "Mutations in the RAB39B gene, which encodes a protein involved in vesicular trafficking, are associated with intellectual disability, but the impact of RAB39B loss of function on synaptic activity is not known." (PMID 25784538, 2015). "Mutations in the RAB39B gene cause intellectual disability comorbid with autism spectrum disorder and epilepsy, but the impact of RAB39B loss of function on synaptic activity is largely unexplained." (PMID 25784538, 2015). "Thus, RAB39B mutations are awell-established cause for intellectual disability, and Parkinsonism, withalpha-synuclein-positive pathology, was observed in some of these patients." (PMID 28733970, 2017). "Interestingly, duplications and triplications of RAB39B lead to intellectual disability and behavioraldisturbances; these mutations have been described in children, some of whom alsohad mild motor symptoms or reached milestones of motor development late." (PMID 28733970, 2017). "VPS13B is indispensable for the Golgi apparatus, and genes important for Golgi morphology and function have been linked to autism disorders, including RAB39B, mutated in a X-linked intellectual disability associated with autism, epilepsy and macrocephaly, and UBE3A, responsible of Angelman syndrome." (PMID 25502226, 2014). "More recently, additional evidence reported that loss-of-function mutations in RAB39B, including whole gene deletion, missense, splicing and frameshift variants, also led to the development of an X-linked form of rare early-onset PD associated with intellectual disability." (PMID 35741861, 2022). "Our results demonstrate that overexpression of RAB39B compromises normal neuronal development, thereby resulting in dysfunctional synaptic transmission and certain intellectual disability and behavioural abnormalities in mice." (PMID 36977207, 2023). "RAB39B c.536dupA (p.E179fsX48) was identifiedin a small Chinese family with two male patients who had learning difficulty fromchildhood and mild intellectual disability." (PMID 28733970, 2017). "Other X-linked forms of mental retardation have been reported in patients with mutations in GDI1, CLIC2, HCFC1, and RAB39B." (PMID 23634718, 2013). "An Xq28 CNV (involving RAB39B gene) was found in a child with intellectual disability and autism (case #48)." (PMID 23272938, 2012). "Pathogenic variants in the gene encoding the small GTPase protein, Ras Analogue in Brain 39b (RAB39B), were initially identified in a few families affected by non-progressive intellectual disability in comorbidity with macrocephaly, autism spectrum disorders and epilepsy." (PMID 35741861, 2022).
Cognitive impairment (11 papers, 2015 to 2025). Abnormal cognition is characterized by deficits in thinking, reasoning, or remembering. "If we consider the cases reported here, it is well confirmed that RAB39B downregulation is associated with severe ID/cognitive impairment and significant behavioural abnormalities (level three severity using ASD standardized tests)." (PMID 34761259, 2022). "Since cognitive impairment is a critical feature of ID as a formal diagnosis of ID is made only when the IQ is scored to be less than 70, our results strengthen the causal effect of RAB39B mutations in the etiology of XLID." (PMID 33364235, 2020). "However, precisely how RAB39B loss-of-function or increased dosage can perturb neuronal development leading to cognitive impairment needs further clarification." (PMID 32873259, 2020). "The gene is located within a chromosomal region that is susceptible to genomic rearrangement, and while an increased dosage of RAB39B was previously associated with cognitive impairment, the potential role of dosage alterations in Parkinson's disease (PD) remains to be determined." (PMID 32670181, 2020). "Future studies will undoubtedly be necessary to answer these questions as well as the availability of Rab39b-null mouse model to better define the link between RAB39B-mediated intracellular trafficking and cognitive disorders." (PMID 25784538, 2015). "Altogether our findings shed light on the molecular mechanisms responsible for the maturation and the trafficking of GluA2/GluA3 AMPAR in the secretory pathway, and pave the way to explain the functional role of RAB39B in cognitive disorder." (PMID 25784538, 2015). "It is suggested that the observed cognitive impairment in this syndrome results from increased dosage of RAB39B gene located within the duplicated region." (PMID 25927380, 2015). "RAB39B and possibly CLIC2 are the most likely candidate genes in which mutations have been reported in individuals with cognitive impairment." (PMID 25927380, 2015). "From the remaining three genes, loss-of-function mutations in both RAB39B and CLIC2 have been reported in individuals with cognitive impairment making it less likely that the hemizygous loss of these genes results in the lethality in males with int22h1/int22h2-mediated deletion." (PMID 25927380, 2015). "However, whether increased dosage of RAB39B leads to cognitive impairment and synaptic dysfunction remains elusive." (PMID 36977207, 2023).
epilepsy (11 papers, 2012 to 2023). A brain disorder characterized by episodes of abnormally increased neuronal discharge resulting in transient episodes of sensory or motor neurological dysfunction, or psychic dysfunction. "In another family (Reference 2), four males with ID, three of whom were also diagnosed with epilepsy, inherited a RAB39B nonsense mutation in exon 1 (hg19: 154,493,553, c.21C>A [p.Tyr7X])." (PMID 29152164, 2017). "It is to note, that RAB39B mutations cause X-linked mental retardation associated with autism, epilepsy, and macrocephaly." (PMID 23272938, 2012). "Mutations in RAB39B cause X-linked intellectual disability and early-onset Parkinson disease with alpha-synuclein pathology, also linked to X-linked mental disability associated with Autism, epilepsy, and macrocephaly." (PMID 34834471, 2021). "RAB39B was first linked to human disease in 2010 when a nonsense and a splice site mutation in the gene were shown to cause mental retardation, sometimes accompanied by epilepsy and autism spectrum disorder, in the male members of two families." (PMID 26399558, 2015). "Pathogenic variants in the RAB39B gene cause X-linked ID with ASD and epilepsy, also comorbid with early-onset PD." (PMID 36835207, 2023). "Based on recent publications, various small GTPases have been identified to contribute to the progression of epilepsy, including Cdc42, RAB39B." (PMID 28255556, 2017).
Parkinsonism (10 papers, 2015 to 2023). Characteristic neurologic anomaly resulting from degeneration of dopamine-generating cells in the substantia nigra, a region of the midbrain, characterized clinically by shaking, rigidity, slowness of movement and difficulty with walking and gait. "Therefore, further genetic and functional studies are required to determine the consequences of dysregulated RAB39B expression and test its potential role as a susceptibility gene associated with PD or parkinsonism more broadly." (PMID 32670181, 2020).
autism (8 papers, 2012 to 2025). Persistent deficits in social interaction and communication and interaction as well as a markedly restricted repertoire of activity and interest as well as repetitive patterns of behavior. "Since loss of function mutations in RAB39B cause ID, autism, and PD symptoms in humans, we next studied whether loss of Rab39b affects mouse behaviors resembling these diseases." (PMID 33364235, 2020). "A genetic deletion that includes the GRIA2 gene encoding GluA2 is associated with autism and mutations of RAB39B that cause intellectual disability comorbid with autism lead to impaired transport of GluA2 to synapses and subsequent shift of AMPAR to higher calcium permeability." (PMID 30800064, 2019). "Neuronaloverexpression of RAB39B impaired the recognition memoryand the short-term working memory in mice and resulted incertain autism-like behaviors, including social novelty defect.Therefore, the pathogenic role of this aberration is uncleardue to limited information in databases." (PMID 41000401, 2025). "We found that at 2 months of age, neuronal overexpression of RAB39B impaired the recognition memory and the short‐term working memory in mice and resulted in certain autism‐like behaviours, including social novelty defect and repetitive grooming behaviour in female mice." (PMID 36977207, 2023).